LGALS3BP (galectin 3 binding protein)
Diseases named in the same sentence as LGALS3BP in open-access papers (continued):
Sharing a sentence is not in itself a finding about the gene and the disease.
Splenomegaly (1 paper, 2021). Abnormal increased size of the spleen. "Lgals3bp−/− mice exhibited significantly greater body weight loss, rectal bleeding, and diarrhea than WT mice and a significant shortening of the colon and splenomegaly, which reflects colonic and systemic inflammation, respectively." (PMID 33824294, 2021).
thymoma (1 paper, 2024). A neoplasm arising from the epithelial cells of the thymus. "Nonetheless, the intricate mechanisms of LGALS3BP involved in thymoma development and progression require further experiments." (PMID 39434140, 2024). "GEPIA validated that LGALS3BP was significantly upregulated in thymoma patients." (PMID 39434140, 2024). "It was determined that LGALS3BP might be an essential biomarker to identify thymoma from the thymic cyst." (PMID 39434140, 2024). "The GEPIA database verified that LGALS3BP is highly expressed in thymoma." (PMID 39434140, 2024). "In this present study, LGALS3BP has been found to be highly expressed in thymoma." (PMID 39434140, 2024). "In conclusion, LGALS3BP might be an essential biomarker to identify thymoma from the thymic cyst." (PMID 39434140, 2024). "It was discovered that A2M, C3, LGALS3BP, PMFBP1, and SRI were remarkably upregulated in individuals with thymoma (P < 0.05)." (PMID 39434140, 2024).
thyroid cancer (1 paper, 2021). "Mice were treated with doxycycline for one week to develop thyroid cancer, and the expression levels of CCL2, CSF-1, LGALS3BP, INPP5D and CCL7, together with that of the chemokine receptors CCR2 and CSF1R, were measured in cancer specimens by quantitative RT-PCR." (PMID 34299284, 2021).
viral encephalitis (1 paper, 2024). Encephalitis resulting from viral infection. "Because severity of illness during viral encephalitis can be due to the extent of CNS inflammation, we analyzed mononuclear cell infiltration and microglial phenotype within the forebrains of WNV-infected 8-week-old Lgals3bp−/− versus WT mice at 8 DPI." (PMID 39062523, 2024).
viral pneumonia (1 paper, 2021). Inflammation of the lung parenchyma that is caused by a viral infection. "Among the signatures associated with the specific efficacy of HYQ against viral pneumonia, Lgals3bp promotes integrin-mediated cell adhesion and may stimulate host defense against viruses." (PMID 34867309, 2021). "With the aid of the discovered biomarkers, we concluded that HYQ has a specific effect on viral pneumonia such as elevated galectin-3-binding protein (Lgals3bp) and glutathione peroxidase 3 (Gpx3) levels in blood." (PMID 34867309, 2021). "Our present study indicates that HYQ can specifically regulate Lgals3bp and Gpx3, thus exerting a good protective effect against viral pneumonia." (PMID 34867309, 2021). "Overall, HYQ may have a specific effect on viral pneumonia such as elevated Lgals3bp and Gpx3 levels in the blood." (PMID 34867309, 2021). "Therefore, Lgals3bp is thought to correspond to the specific efficacy of HYQ against viral pneumonia." (PMID 34867309, 2021).
cancer (97 papers, 2005 to 2026). A tumor composed of atypical neoplastic, often pleomorphic cells that invade other tissues. "LGALS3BP is implicated in the growth and progression of various cancer types, with its protumor activity primarily associated with its secreted form, which depends on N-glycosylation." (PMID 39937175, 2025). "LGALS3BP (galectin 3 binding protein) is a multifunctional glycoprotein implicated in immunity and cancer." (PMID 38393692, 2024). "Recently, it has become clear that LGALS3BP associated with extracellular vesicles is a key regulator of intercellular and extracellular matrix crosstalk in the context of cancer." (PMID 39434140, 2024). "In BC biopsies, the overexpression of cancer cell-associated LGALS3BP was detected at the edges of tumors, where the cancer cells invade the surrounding stroma." (PMID 37092454, 2023). "LGALS3BP is a heavily glycosylated secreted molecule with an immunoinhibitory function often found to be upregulated in cancer, but has also been implicated in various other diseases (e.g., RA)." (PMID 35033099, 2022). "Our glycoproteomic results indicated that 2DG led to the changes in N-glycosylation of some well-known cancer-associated glycoproteins, including LGALS3BP, CEACAM1, and EGFR." (PMID 35897829, 2022). "The analysis of different cancer data sets included in the public cBioPortal platform revealed a general association between high tumor levels of LGALS3BP (both mRNA and protein) and shorter survival in patients affected by different types of cancer." (PMID 33888686, 2021). "In conclusion, further studies are needed to fully exploit the potential of LGALS3BP as a diagnostic marker, a driver of malignancy and progression as well as a therapeutic target in cancer." (PMID 34565385, 2021). "The lectin galactoside-binding soluble 3 binding protein (LGALS3BP), a large oligomeric glycoprotein, is overexpressed in many cancers and always associated with cancer growth and migration." (PMID 34760348, 2021). "More recently, it was also clear that extracellular vesicles—associated LGALS3BP is a key regulator in cell–cell and cell-extracellular matrix cross-talk in the cancer context." (PMID 34565385, 2021). "LGALS3BP, also known as Mac-2 binding protein (Mac-2BP) or tumor-associated antigen 90K, is a secreted glycoprotein that has been widely studied as a marker for cancer progression and metastasis." (PMID 34900729, 2021). "LGALS3BP encodes the galectin-3-binding protein (Gal-3BP), which was originally reported by several groups in attempts to search for proteins secreted by cancer cells." (PMID 31402917, 2019). "LGALS3BP, or Galectin-3-binding protein, promotes integrin-mediated cell adhesion associated with cancer." (PMID 29868478, 2018). "Glycoprotein 90K (also known as LGALS3BP or Mac-2BP) is a tumor-associated protein, and high 90K levels are associated with poor prognosis in some cancers." (PMID 29207493, 2017). "On the other hand, binding of LGALS3BP to integrin on tumor cells activates the Akt and Raf-Erk pathways, which was associated with increased survival, proliferation, motility, and migration of cancer cell lines." (PMID 35038949, 2022). "Furthermore, CRC patients exhibiting high Lgals3bp expression in cancer tissues have a lower relapse risk and longer overall survival than those exhibiting low Lgals3bp expression." (PMID 33824294, 2021). "Higher serum LGALS3BP levels have been linked to poor prognosis and progression in various cancers." (PMID 32542012, 2020). "Moreover, data from our group and other have strongly suggested that this protein is enriched in cancer-associated extracellular vesicles and may be considered a promising candidate for a targeted therapy in LGALS3BP positive cancers." (PMID 34565385, 2021). "LGALS3BP has been reported to be one of the most abundant proteins in extracellular vesicles isolated from individuals with cancer." (PMID 40987065, 2025).
cancer (continued). "LGALS3BP has been studied in the context of cancer biology, and more recently, its neurological involvement has been described in the process of neurodevelopmental corticogenesis." (PMID 41103078, 2025). "Initially identified for its role in cancer development, LGALS3BP has emerged as a potential therapeutic target." (PMID 41090922, 2025). "Lgals3bp is commonly enriched in extracellular vesicles from tumor cells, and its serum level has been shown to be a prognostic indicator in various cancers." (PMID 38279161, 2024). "The results of the cancer stemness index proved that the index was obviously related to LGALS3BP expression and tumor metastasis." (PMID 38393692, 2024). "Further exploration of Open Targets demonstrated that LGALS3BP plays a vital role in the immune system, cancer, and urological diseases." (PMID 38393692, 2024). "Galectin-3-binding protein seems to participate in several pro-tumoural mechanisms in a variety of cancers." (PMID 37580662, 2023). "Previously, we reported lectin galactoside-binding soluble 3 binding protein (LGALS3BP) as a negative regulator of TAK1 signaling in the inflammatory response and inflammation-associated cancer progression." (PMID 37041137, 2023). "Consistent with our finding, individual cancer-specific EMT signature genes such as PDIA3, HLA-A, BCAM, B2M, LGALS3BP, and HLA-C were highly expressed in cancer cells from infiltrated and excluded TMEs." (PMID 38086828, 2023). "Moreover, a characterization of LGALS3BP glycosylation pattern could be useful to discriminate whether the vesicular forms isolated from cancer patients may differ from that obtained from healthy samples, thus increasing the specificity of LGALS3BP as a GBM associated marker." (PMID 37195369, 2023). "Galectin 3-binding protein (LGALS3BP), alternatively known as 90K, is a versatile glycoprotein that plays multifaceted roles in both immune responses and cancer-related processes." (PMID 37945594, 2023). "Another potent cancer biomarker for which a SERS-based immunoassay has been developed is galectin-3-binding protein (LGALS3BP), also known as 90K, a protein involved in tumor growth and progression." (PMID 37241360, 2023). "LGALS3BP is a glycosylated protein expressed and secreted by cancer cells which have emerged as a key player in regulating cancer–stroma interaction, being one of the most abundant surface components of cancer‐derived EVs." (PMID 37195369, 2023). "Among them, TIMP1, LGALS3BP, A2M, AHSG, FN1, HRG, and ITIH4 have been associated with cancer, while CF I, C2, and C4A, have been related to complement activity." (PMID 37685286, 2023). "Zhang and colleagues (2019) were the first to link the enrichment of LGALS3BP, a sialoglycoprotein, to the EV subclass exomeres (diameter ~35 nm) by using asymmetric field flow fractionation of cancer cell lines." (PMID 35736799, 2022). "Here, we study the role of LGALS3BP, so far known as a cancer biomarker, which is a secreted protein enriched in human neural progenitors (NPCs)." (PMID 34728600, 2021). "A large body of data have been collected so far, which has indubitably revealed the role of LGALS3BP as a prognostic marker in a variety of cancer disease." (PMID 34565385, 2021). "According with this findings, functional analysis demonstrated that LGALS3BP overexpression is correlated with the occurrence, proliferation, differentiation and metastasis of cancer cells." (PMID 34565385, 2021). "LGALS3BP has been found in diverse cancer-derived exosomes, and APOE has been found in exosomes released from macrophages and neurons." (PMID 34660591, 2021). "Since its discovery dated in early 90 s, a large body of literature has been accumulating highlighting both a prognostic and functional role for LGALS3BP in cancer." (PMID 34565385, 2021). "It appeared that expression of LGALS3BP by cancer cells was critically regulated, and an optimal expression level was required for evading the immune response and to colonize distant tissues." (PMID 34565385, 2021).
cancer (continued). "Here, we extensively reviewed the literature relative to LGALS3BP role in cancer and its potential value as a therapeutic target." (PMID 34565385, 2021). "In line with this, using an innovative ADC-based therapy, our group has recently opened the way to anti-LGALS3BP therapy highlighting the potential of this molecule as target for cancer therapy." (PMID 34565385, 2021). "Because Lgals3bp expression is increased in cancer patients, its role in cancer has been widely studied." (PMID 33824294, 2021). "It was demonstrated that LGALS3BP destabilizes E-cadherin–p120-catenin complex through ubiquitination proteasomal degradation, promoting the release and motility of cancer cells from tumor tissues through the weakening of cell–cell adherens junctions." (PMID 34565385, 2021). "This review summarizes the current knowledge of structural features of LGALS3BP, its pattern of expression in cancer and the potential role as novel therapeutic target in cancer." (PMID 34565385, 2021). "Although the current evidence regarding Lgals3bp activity in cancer is controversial, Lgals3bp exhibits anti-tumor activity in CRC cells." (PMID 33824294, 2021). "Like S100A8/A9, LGALS3BP is expressed in a number of human cancer entities, though its putative oncogenic role is only poorly understood." (PMID 32503348, 2020). "LGALS3BP (Galectin- 3 binding protein, aka Mac-2 BP or 90K), is a human secreted protein expressed by the large majority of human cancers, while being virtually undetectable or expressed at low levels in normal human tissues." (PMID 33076448, 2020). "Although galectin-3-binding protein has been reported to be elevated in HIV infection and cancer, the cause of its elevation in either disease is unclear in vivo." (PMID 24597896, 2014). "LGALS3BP, also known as 90K, is a highly glycosylated, secreted protein extensively studied in human cancer." (PMID 25360666, 2014). "LGALS3BP is a secreted glycoprotein that has been found in the extracellular matrix and in body fluids, in exosomes from cancer cells, urinary and plasma exosomes and in prostasomes, which are exosome-like vesicles secreted by the prostate." (PMID 24302979, 2013). "LGALS3BP/90K is a multifunctional glycoprotein originally identified in cancer progression." (PMID 40542445, 2025). "Furthermore, intracellular centriole biogenesis and centrosome hypertrophy in cancer cells can be regulated by LGALS3BP to inhibit TAK1-dependent NF-κB activation." (PMID 38393692, 2024). "Overexpression of LGALS3BP has been reported in various other carcinoma types." (PMID 39434140, 2024). "Therefore, further studies are required to identify the domain or amino acid sequence of LGALS3BP responsible for TAK1 interaction and inhibition for developing LGALS3BP-derived anti-cancer peptides." (PMID 37041137, 2023). "LGALS3BP has been found to be elevated in the serum of patients with cancer." (PMID 35865015, 2022). "Moreover, elevated expression levels of LGALS3BP in serum and tumor tissue of cancer patients have been found and positively correlated with a poor survival or a more advanced and/or metastatic disease in the large majority of solid human cancers." (PMID 34565385, 2021). "A second report confirmed importance of LGALS3BP in EC-derived exosomes, trough proteomic analysis and ELISA revealing that plasma exosomal LGALS3BP increased during EC progression, and it promoted cancer cell growth and angiogenesis via PI3K/AKT/VEGFA signaling." (PMID 34565385, 2021). "Therefore, further studies are required to investigate the role of LGALS3BP in various aspects of cancer." (PMID 33824294, 2021). "Although LGALS3BP was originally identified in cancer cells, its role in tumorigenesis remains unclear." (PMID 33824294, 2021). "In addition, in cancer cells, there was a strong tendency of co-occurrence between high LGALS3BP, high USF1, high USF2, and high TGF-β1 expression (p < 0.001) or low LGALS3BP, low USF1, low USF2, and low TGF-β1 expression (p < 0.001)." (PMID 33888686, 2021).
cancer (continued). "Based on the various functions of TAK1, LGALS3BP might inhibit tumorigenesis and cancer progression by suppressing tumor cell proliferation, metastasis, and anti-cancer drug resistance." (PMID 33824294, 2021). "Galectin-3 binding protein (Gal-3BP), also known as Mac-2 binding protein, is a ubiquitous and multifunctional secreted glycoprotein found in human serum, Increased Gal-3BP levels have been reported in various infections and in several types of cancer." (PMID 35062248, 2021). "Whereas the bio-physiological role of LGALS3BP is not yet fully understood, accumulating evidence has shown that the protein may be involved in cancer growth and progression." (PMID 33076448, 2020). "90K, also known as LGALS3BP, galectin-3-binding protein (Gal-3BP) and Mac-2-binding protein, is a ubiquitous multifunctional secreted glycoprotein originally studied in the context of neoplastic transformation and cancer progression." (PMID 31404116, 2019). "The mechanism of LGALS3BP leading to malignant tumor remains uncertain." (PMID 27825122, 2016). "Many reports suggest that CLIC1 and LGALS3BP locate in cell membrance and might promote the tumor progression of other cancers." (PMID 27825122, 2016). "Furthermore, LGALS3BP possibly promotes cancer formation by regulating integrin mediated cell adhesion pathway and angiogenesis through PI3K/AKT pathway." (PMID 27825122, 2016). "However, we observed that the N-glycopeptides of several cancer-associated proteins (e.g., EGFR, LGALS3BP, and PLOD3) were down-regulated in hiPSCs compared to hESCs." (PMID 27808266, 2016). "In contrast, positive effects of LGALS3BP on cancer prognosis have also been reported." (PMID 26219351, 2015). "Moreover, the level of circulating EVs‐associated LGALS3BP positively correlated with tumour burden, thus suggesting that vesicular LGALS3BP released from GBM cancer cells may be used as potential circulating disease marker." (PMID 37195369, 2023). "Mechanically, on the one hand, as a secretory glycoprotein, LGALS3BP interacts with extracellular matrix elements and members of the galectin family, facilitating cell adhesion to matrix proteins by interaction with β1 integrin subunits which play important role in cancer metastasis." (PMID 35038949, 2022). "Therefore, as summarized in this review behind the notion that LGALS3BP may serve as an attractive therapeutic target in cancer, there is a strong rationale." (PMID 34565385, 2021). "Notably, high LGALS3BP expression is a marker of activated tumor-stroma, angiogenesis, and metastasis, and high LGALS3BP levels correlate with poor survival in some types of cancers." (PMID 32503348, 2020). "Indeed, LGALS3BP is one of the most abundant surface component of cancer-derived EVs." (PMID 33076448, 2020). "Interestingly, several of the proteins that exhibited alterations in N-glycoprotein expression levels (e.g., EGFR (epidermal growth factor receptor), LGALS3BP (Galectin-3-binding protein) and PLOD3 (Procollagen-lysine, 2-oxoglutarate 5-dioxygenase 3)) in hiPSCs are linked with cancer." (PMID 27808266, 2016). "Taken together, these observations strongly indicate that LGALS3BP is homogenously overexpressed in GBM compared to peritumoral tissues and enriched in cancer‐released EVs." (PMID 37195369, 2023). "We focused on LGALS3BP, which was shown to be particularly up-regulated in MTX-resistant cells and had been proven to be an oncogene in several cancers, while its function in the regulation of MTX resistance in GTNs still remains poorly understood." (PMID 35038949, 2022). "The lectin galactoside-binding soluble 3 binding protein (LGALS3BP), a ligand for human Siglec9, is upregulated in the ECM of PCa specimens and can inhibit neutrophils activation, supporting immune escape of cancer cells." (PMID 36338516, 2022).